MMP2 (matrix metallopeptidase 2)
Diseases named in the same sentence as MMP2 in open-access papers (continued):
Sharing a sentence is not in itself a finding about the gene and the disease.
gastric cancer (continued). "Using immunohistochemical analysis, the present study showed that the expression of claudin-4 was found to correlate with tumor invasion and MMP-2 and -9 expression in gastric cancer." (PMID 25120725, 2014). "The devised MMP2 aptamer precipitated and detected MMP2 protein in pathological tissues, that is, atherosclerotic plaques and gastric cancer tissues." (PMID 24589243, 2014). "A synthetic small-molecule pan-PI3K inhibitor, LY294002, significantly inhibits the growth of gastric carcinoma while promoting apoptosis, resulting in the downregulation of MMP-2, MMP-9, and VEGF." (PMID 25003395, 2014). "Meanwhile, our previous study had showed that Bcl-w-induced Sp1 expression contributed to invasiveness by activating MMP-2 in gastric cancer cells." (PMID 23826359, 2013). "In vitro experiments showed that Mfn2 overexpression suppressed gastric cancer cell proliferation and colony formation, weakened the invasion and migratory ability of cancer cells by downregulating MMP-2 and MMP-9, halted the cell cycle and induced apoptosis." (PMID 23797661, 2013). "In our study, it was showed that downregulation of CD147 expression in human gastric cancer cells reduced the secretion of MMP-2 and MMP-9, thus inhibited the invasion ability of gastric cancer cells through the reconstituted basement membrane in vitro." (PMID 20525232, 2010). "For example, the expression of several extracellular matrix metalloproteinases (MMP-2, 7, 9) has been found to be elevated in gastric cancer tissues compared to healthy gastric tissues." (PMID 20529313, 2010). "The results showed that MMP-2, MMP-7, MMP-9 and MT1-MMP were all significantly upregulated in gastric cancer specimens compared to matched normal tissue specimens (For both MMP-2 and MMP-9, P < 0.01; for both MMP-7 and MT1-MMP, P < 0.001)." (PMID 19586554, 2009). "Our initial finding showed that SFRP5 expression is significantly downregulated in gastric cancer, while the subsequent quantitative real-time PCR analysis revealed that MMP-2, MMP-7, MMP-9 and MT1-MMP are all upregulated in it." (PMID 19586554, 2009). "We studied the genotype distribution and allele frequencies of SNPs of MMP-2, -7, -8 and -9 and TIMP-1 and -2 in gastric cancer patients in relation to tumour progression, patient survival and tissue antigen expression." (PMID 16940985, 2006). "This underscores the role of MMP-2 in breaking down the extracellular matrix in early gastric cancer which has been suggested before." (PMID 16940985, 2006). "The optimal cutoff point for MMP-2 antigen calculated for survival prognosis in the old group of patients was similarly predictive in the new group of patients, indicating the strength of MMP-2 as a prognostic indicator for gastric carcinoma patients." (PMID 16538217, 2006). "The value of MMP-2 as an independent prognostic marker for gastric carcinomas is underscored by our observation that MMP-9, MMP-7, MMP-8, TIMP-1 and TIMP-2 have no prognostic relevance." (PMID 16538217, 2006). "Overexpression of all the gelatinases occurs in both colorectal and gastric cancer, with activation of MMP-2 appearing to be a feature of the malignant phenotype." (PMID 9836483, 1998). "The aim of the study was to investigate expression of the active and inactive gelatinases (MMP-2 and -9) in colorectal neoplasia and gastric cancer compared with normal mucosa." (PMID 9836483, 1998). "Notably, our research offers the first proof that DZN and PNR together operate as an anti-cancer drug by blocking MMP-2 production in human gastric cancer cells through the STAT3/FAK signalling pathways." (PMID 40217305, 2025). "MMP2 emerged as a promising target for gastric carcinoma detection and treatment." (PMID 39773048, 2025). "High levels of MMP-2, MMP-9, and vascular endothelial growth factor (VEGF) have been closely linked to cell growth, dissemination, metastasis, and the development of new blood vessels in gastric cancer." (PMID 38374934, 2024).
gastric cancer (continued). "Moreover, SNHG15 can promote the proliferation and invasion of gastric cancer cells by regulating the expression of MMP2 and MMP9 proteins." (PMID 38526609, 2024). "In addition, the absence of CDK5RAP3 in gastric cancer cells induces macrophages to secrete high levels of MMP2, thereby promoting the migration and invasion of gastric cancer cells." (PMID 35999359, 2023). "MMP-2 is considered to be a prognostic marker in patients with gastric cancer." (PMID 37047765, 2023). "Besides, high expression of five genes, POSTN, COL5A2, COL1A1, FN1, and MMP2, was revealed by Kaplan–Meier survival curve analysis to suggest a poor prognosis for gastric cancer patients." (PMID 37461041, 2023). "In vivo bioluminescence imaging showed that low expression of CDK5RAP3 significantly increased the in-situ proliferation of gastric cancer cells compared with the control group, while the MMP2 inhibitor reversed the increase in proliferation induced by low CDK5RAP3 expression." (PMID 35999359, 2023). "Further analysis in chick chorioallantoic membrane assays showed that OA treatment significantly promoted the invasiveness of gastric cancer cells and induced the expression of MMP-2 in gastric cancer cells by activating the PI3K/Akt signaling pathway in a PTEN-independent manner." (PMID 37373069, 2023). "The gelatinases MMP2 and -9 are crucial in invasion and metastasis and in several tumor entities, and the MMP9 promoter allele Rs3918242 is associated with a higher risk of metastasis in gastric cancer." (PMID 35269560, 2022). "MMP-2/9 is a member of the MMPs family that is highly expressed in colorectal cancer, gastric cancer, and nasopharyngeal carcinoma and closely related to tumor invasion and fibrosis, and knockdown of LAP3 can reduce MMP-2/9 expression and consequently cell invasion." (PMID 36311709, 2022). "Further analysis of MMP2 protein expression in a cohort of gastric cancer was performed using IHC." (PMID 35397606, 2022). "Combined mRNA expression of MMP2 and ATF1 was associated with gastric cancer survival." (PMID 35397606, 2022). "To determine whether the pro-invasive and -metastatic effects of gastrin involve MMP-2 and VEGF in gastric cancer cells, we detected the mRNA and protein expression and secretion of MMP-2 and VEGF in gastrin-overexpressed and gastrin-knocked down cells." (PMID 34976177, 2022). "Moreover, the expression of p-ATF1-T184 was positively correlated with MMP2 in gastric cancer tissues." (PMID 35397606, 2022). "We found that the forced gastrin could promote the proliferation, migration, and invasion of gastric cancer cells by upregulating the expression of MMP-2 and VEGF." (PMID 34976177, 2022). "Gastric cancer cells (SGC-7901 and BGC-823) were found to be the most sensitive to Latcripin-1, mainly due to induction of cell cycle arrest at S phase and the induction of autophagy, but also attributed to the reduced MMP-2/9 levels responsible for gastric cancer migration and invasion." (PMID 34444724, 2021). "Since STAT3 phosphorylation is a crucial event in the signaling pathway, triggered by IL-6 in MMP-2 up-regulation in gastric cancer cells, we analyzed the STAT3 phosphorylation status following the rIL-6 exposure before and after preincubation with LPE in T88 and T93 cells." (PMID 34885656, 2021). "In addition, PTGER3 can also up-regulate the expression of related MMP2 and AR to promote the proliferation of cancer cells and the deterioration of gastric cancer." (PMID 34646828, 2021). "For example, in gastric cancer, the MMP1 and MMP2 increased expression is related to the loss of E-cadherin expression, thereby, leading cancer proferliation and metastasis.MMP-3 and MMP-7 have association with the development of Helicobacter pylori-related gastric cancer." (PMID 34422902, 2021).
gastric cancer (continued). "A previous research confirmed the robust correlation between high MMP-2/9 expression and metastasis in human gastric cancer; hence, their overexpression could be a valuable predictor of poor prognosis in patients with gastric cancer." (PMID 33964908, 2021). "In addition, AT1R antagonist also prevented gastric cancer progression by blocking the angiotensin II-induced overexpression of matrix metallopeptidase-2 (MMP-2) and MMP-9, critical components mediating tumor migration and invasion." (PMID 34831211, 2021). "They found that MMP-2 overexpression was a predictive factor for poor prognosis of gastric cancer." (PMID 34027107, 2021). "In addition, a number of meta-analyses found that overexpression of MMPs was associated with poor prognosis in gastric cancer patients, as was the case for MMP-9 and MMP-2." (PMID 32046329, 2020). "Further, it was reported that knockdown of β-1, 3-N-acetyl glucosaminyltranferase-8 in gastric cancer cells could suppress invasive potential, which was correlated with reduced MMP-2 expression and activity levels." (PMID 32260356, 2020). "Additionally, antimetastatic potential of PCA in human gastric carcinoma AGS cells was mediated via the inhibition of MMP-2 secretion." (PMID 32028623, 2020). "However, our previous research results instead found that LOX and MMP-2 are positively correlated at the mRNA and protein levels in gastric cancer tissues." (PMID 31777578, 2019). "However, our previous study found that expression of LOX and MMP-2 are positively correlated in gastric cancer tissues, and they play synergistic roles in promoting the invasion and metastasis of gastric cancer." (PMID 31777578, 2019). "In addition, a recent study also indicated that PAK1 promotes the invasion of gastric cancer cells by inducing the mRNA expression and activity of MMP-2." (PMID 30971268, 2019). "Furthermore, an elevated expression of MMP-2 was correlated with VEGF expression in gastric cancer which suggests that this MMP plays a critical role in the progression of cancer through ECM degradation, tumor neovascularization and metastasis." (PMID 31921634, 2019). "Similarly, knocking down their expression significantly inhibited the invasive and migratory phenotypes of human gastric cancer SNU484 cells by inhibiting MMP-2 expression." (PMID 29416786, 2018). "In addition, ursolic acid also suppressed expression of MMP-2, as well as declined invasion and migration in these lung and gastric cancer cells." (PMID 29356905, 2018). "In the present study, we investigated whether CH-5 has antiproliferative and pro-apoptotic properties and, finally, whether CH-5 inhibits migration and invasion in gastric cancer cells by reducing the expression of MMP-2." (PMID 29385675, 2018). "The upregulation of HSF1 in gastric cancer cells stimulates the expression of MMP2, MMP7 and MMP9." (PMID 30326922, 2018). "Overexpression of MMP-2 is related to distant metastasis of gastric cancer patients." (PMID 29358963, 2017). "However, the pretreatment of RAGE-specific blocking antibody diminished AGEs-induced effects, which suggested that the AGEs-RAGE interaction increased the expression of Sp1 and MMP2 in gastric cancer cells." (PMID 29262634, 2017). "Besides, knockdown of SNHG15 significantly inhibited cell proliferation and invasion and promoted apoptosis, whereas forced expression of SNHG15 exhibited the opposite effects on gastric cancer cells via regulating MMP2 and MMP9 protein expression." (PMID 28720111, 2017). "Furthermore, they demonstrated that miR-29 family directly targeted CCND2 and MMP2 to influence gastric cancer progression." (PMID 28173777, 2017). "PEITC suppresses metastasis of human gastric cancer cells by inhibiting MMP-2 and MMP-9." (PMID 28969043, 2017). "SLPI promoted migration, invasion and metastasis of gastric cancer cells by increasing expression of MMP-2 and MMP-9 genes, and the latter could have been targeted by transcriptional factor FoxM1." (PMID 29312532, 2017).
gastric cancer (continued). "Importantly, the enzymatic assay revealed an increase in MMP2 degradation of the ECM in gastric cancer tissues obtained from patients with the MMP2 rs2285053 CC genotype." (PMID 29285307, 2017). "upregulation of Dll4 increases expression of MMP-2 and promotes progression of gastric cancer." (PMID 28881855, 2017). "We detected suppression of VEGF-A and MMP-2 in NDV-D90-treated gastric cancer cells." (PMID 28388537, 2017). "This up‐regulation of TAGLN in CAFs is in agreement with studies demonstrating up‐regulation of this protein in the majority of PCa‐derived CAFs and in gastric carcinoma‐derived CAFs where it regulates CAF‐mediated metastasis of cancer cells through the regulation of MMP2 expression." (PMID 28510269, 2017). "LINC00152 could directly bind to EGFR and activate EGFR signaling pathway and FENDER could suppress cell invasion and migration by downregulating FN1 and MMP2/MMP9 expression in gastric cancer." (PMID 27966444, 2016). "Gastric cancer metastasis-associated genes, including hypoxia-inducible factor (HIF)-1α, matrix metalloproteinase (MMP)-2, MMP-9, basic fibroblast growth factor (bFGF), and urease plasminogen activator (uPA) were measured by RT-sqPCR prior to and following transfection with the KAI1 gene." (PMID 26622792, 2015). "Further insights into the functional and clinical implications of FENDRR and its targets FN1 and MMP2/MMP9 may help with the treatment of gastric cancer." (PMID 25167886, 2014). "In addition, overexpression of claudin-4 in gastric cancer cells was shown to lead to increased expression of MMP-2 and -9, thus, suggesting a mechanism for the increased invasive potential of claudin-4-expressing gastric cancer cells." (PMID 25120725, 2014). "Recent studies suggested that RNAi-mediated down-regulation of CD147 decreased cell proliferation, MMP-2 and MMP-9 activities and the invasive potential of SGC7901 cells, which support our results demonstrating the association of CD147 with gastric cancer invasion and metastasis." (PMID 24979746, 2014). "To figure out the possible mechanisms of how IGFBP3 regulate the invasiveness of gastric cancer cells, we examined the mRNA levels of MMP2/MMP7/MMP9/MMP14, TIMP1/TIMP2, uPA and its receptor uPAR, all of which are invasion-related factors, especially in gastric cancer." (PMID 24386080, 2013). "Correlation analysis between CXCR1/2 and pAKT (P=0.032), pERK (P<0.001), Cyclin D1 (P=0.049), EGFR (P=0.013), Bcl-2 (P=0.003), microvessel density (P=0.001), MMP-9 (P=0.013) and MMP-2 (P=0.027) expression using the Spearman test showed significant correlation in gastric carcinoma." (PMID 23420470, 2013). "Our data show the effect ofppGalNAc-T2 on proliferation, adhesion or invasion of SGC7901 gastric cancer cells,suggesting that ppGalNAc-T2 may exert anti-proliferative and anti-metastatic activitythrough the decrease of MMP-2 and TGF-β1." (PMID 22992780, 2012). "Moreover, knockdown of CTGF expression also markedly reduced the migration and invasion of gastric cancer cells and decreased the expression of matrix metalloproteinase (MMP)-2 and MMP-9." (PMID 21955589, 2011). "Recently, we demonstrated that p37 may promote gastric cancer cell invasion and metastasis by increasing the activity of MMP-2 and by inducing EGFR phosphorylation, therefore contributing to tumor metastasis upon Mycoplasma hyorhinis infection." (PMID 21062494, 2010). "This association might be caused by the noninvasion-related activities of MMPs, like cytokine release/activation, which makes MMP-2 in our opinion an important player in gastric cancer, deserving further investigation." (PMID 16538217, 2006). "The present study corroborates our previous finding of increased MMP-2 in gastric cancer." (PMID 16538217, 2006).
gastric cancer (continued). "In the present study, we determined the genotype distribution and allele frequencies of SNPs of MMP-2, -7, -8 and -9, and of TIMP-1 and -2 in a cohort of 79 Caucasian gastric carcinoma patients, in which we previously assessed clinical relevance of the respective protein levels." (PMID 16940985, 2006). "Consequently, these results indicated that the lack of CDK5RAP3 in gastric cancer enhances the EMT process of gastric cancer cells by promoting the secretion of MMP2 by TAMs in vitro, thereby enhancing the proliferation, invasion, and migration ability of gastric cancer cells." (PMID 35999359, 2023). "This study figured out the role of p-ATF1-T184 in the metastasis of gastric cancer (GC) and in the regulation of Matrix metallopeptidase 2 (MMP2)." (PMID 35397606, 2022). "The expression of p-ATF1-T184 and MMP2 could be a prognosis marker of gastric cancer patients." (PMID 35397606, 2022). "In addition, an elevated expression of MMP-9 and downregulation of E-cadherin have been found to associate with poorly differentiated gastric carcinoma and lymph-node metastasis, and together with increased levels of VEGF and MMP-2, they can serve as malignancy markers in gastric cancer." (PMID 35163805, 2022). "Mechanistically, IL-32 has been demonstrated to promote changes in gastric cancer cell morphology, facilitating their migration, and to enhance their potential for invasiveness by upregulating the expression of matrix metalloproteinases (MMP)-2 and 9, VEGF-A, and IL-8 via HIF-1α activation." (PMID 33020452, 2020). "In addition, co-culture of gastric cancer cells and tumor-associated lymphatic endothelial cells (LECs) elevated CXCL1 secretion in LECs which in turn upregulated integrin β1 and MMP2/9 that promotes cell adhesion, migration, invasion and lymph node metastases." (PMID 33414786, 2020). "Therefore, 28-hydroxy-3-oxoolean-12-en-29-oic acid may inhibit the invasion and migration of gastric cancer cells by downregulating the protein expression of MMP-2 and MMP-9." (PMID 31569766, 2019). "We also demonstrated that knocking down EHF expression in gastric cancer cells significantly inhibited expression of MMP-2, -7, -9 and -14 genes, suggesting that the decrease in the metastasis-related phenotypes may be associated with suppression of expression or activities of MMPs." (PMID 27787520, 2016). "We also demonstrated that AIB1 down-regulation significantly inhibited expression of MMP-2, -7, -9 and -14 genes in gastric cancer cells, suggesting that the decrease in the metastasis-associated phenotypes may be mediated by suppressing expression or activities of MMPs." (PMID 25970779, 2015). "Furthermore, the claudin-4-expressing gastric cancer cells were found to increase MMP-2 and MMP-9 expression, indicating that claudin-mediated increased cell invasion may be the result of MMP protein activation." (PMID 25120725, 2014). "This study was to determine the roles of MMP-9, MMP-2, type IV collagen, infiltrating macrophages and tumor microvessels in gastric cancer (GC) invasion and their clinico-pathological significance." (PMID 20950454, 2010). "Factors such as MMP2 and MMP9 enhance NKG2D expression, “sensitizing” gastric cancer cells to NK cell-mediated attack." (PMID 40136652, 2025). "In this study, we provide the first evidence that the combination of DZN and PNR significantly inhibits gastric cancer cell migration and invasion by downregulating STAT3/FAK signaling and suppressing MMP-2 expression." (PMID 40217305, 2025). "It is well established that MMP-2, MMP-9, and MMP-11 contribute to the remodeling of the tumor microenvironment (TME) in gastric cancer through both structural and functional mechanisms." (PMID 40906383, 2025). "Western-blotting was used to detect the protein expression of EMT/ metastasis related markers MMP-2, MMP-9, N-cadherin, Zeb1, Vimentin, Snail and E-cadherin in gastric cancer cells." (PMID 40265472, 2025).